GABPA (GA binding protein transcription factor subunit alpha)
Diseases named in the same sentence as GABPA in open-access papers (continued):
Sharing a sentence is not in itself a finding about the gene and the disease.
tumor (continued). "One study indicated that abnormal expression of GABPA has relationship with progression of HCC and this transcription factor acted as a tumor suppressor." (PMID 35958019, 2022). "GABPA acts as a tumor suppressor by stimulating TGFBR2 expression and TGFβ signaling, while L-2-HG epigenetically inhibits GABPA expression, disrupting the GABPA-TGFβ loop to drive ccRCC aggressiveness." (PMID 35549739, 2022). "GABPA has tumor suppressor roles as well through the regulation of DICER1, which is responsible for multiple tumor suppressor mechanisms involving the miRNA pathway." (PMID 33257697, 2020). "To conclude, we show that GABPA directly regulates DICER1 in FTC, acting as a tumour suppressor and displaying down-regulation in clinical samples." (PMID 32163919, 2020). "The results of the chi-square test indicated that abnormal expression of GABPA in HCC tissues was related to alpha-fetoprotein (AFP) levels (P = 0.001), tumor grade (P = 0.017), and tumor distant metastasis (P = 0.021)." (PMID 28549418, 2017). "Mechanistically, GABPA inhibits P4HA2 expression, thereby reducing collagen cross-linking, whereas GABPA downregulation promotes ECM remodeling, increases tumor stiffness, and results in the acquisition of invasive phenotypes via the mechanotransduction pathway." (PMID 40813762, 2025). "These investigations demonstrated a correlation between reduced amounts of the transcription factor GABPA (GA repeat binding protein alpha) and lower levels of DICER, as well as an increase in tumor invasion, neoplastic cell proliferation, and overall tumor call viability." (PMID 39857323, 2025). "By doing so, we observe that GABPA acts as a tumor suppressor by stimulating TGFBR2 transcription and TGFβ signaling, while the oncometabolite L-2-HG epigenetically inhibits GABPA expression, disrupting the GABPA-TGFβ loop to drive ccRCC aggressiveness." (PMID 35549739, 2022). "Given these biological functions and its frequent methylation and/or deletion, GABPA serves as a tumor suppressor rather than oncogenic factor in BC." (PMID 31802036, 2020). "In addition to the targets that we identified by RNA sequencing, miR-378a-5p has been shown to be involved in tumorigenesis and tumor maintenance by regulating SUFU, TUSC2, TOB2, GABPA and ESRRg." (PMID 24651706, 2014). "Notably, four of these TFs—RUNX3, GABPB1, GABPA, and BCL6B—are known tumor suppressors." (PMID 40432923, 2025). "Based on the cellular experiments, GABPA inhibits P4HA2 expression, thereby resulting in reduced Col I and III formation and maturation, and we thus sought to assess whether these effects contributed to altered tumor ECM stiffness." (PMID 40813762, 2025). "However, in MCF-7 tumor cells no GABPA was detected on the TERT promoter." (PMID 33257697, 2020). "The presence or absence of the GABPA TF site in TERT promoters of rodents correlates with TERT promoter activity; thus it could determine whether replicative senescence plays a tumor suppressor role in these species, which could be in direct relation with body mass." (PMID 33257697, 2020).
infection (1 paper, 2021). The state of being infected such as from the introduction of a foreign agent such as serum, vaccine, antigenic substance or organism. "The transcription factors GABPA, ZNF579, SP110, and TSC22D2 were also induced after infection." (PMID 34777295, 2021).
GABPA also shares sentences with these, for which no sentence is quoted: leukemia (2 papers); Parkinson disease (2); anaplastic thyroid carcinoma (1); brain disorder (1); cardiovascular diseases (1); Cirrhosis (1); CNS tumors (1); cognitive diseases (1); COVID-19 (1); diabetic nephropathy (1); endometriosis (1); gastric cancer (1); gout (1); heart failure (1); hypothyroidism (1); Immunodeficiency (1); Insulin resistance (1); porphyria (1); sarcoma (1); schizophrenia (1); Zinc deficiency (1).